IL6 (interleukin 6)
Diseases named in the same sentence as IL6 in open-access papers (continued):
Sharing a sentence is not in itself a finding about the gene and the disease.
tumor (continued). "DC maturation is inhibited in many cancers, as a consequence of secretion of tumor cell-derived immunosuppressive factors, such as IL-10, transforming growth factor (TGF)-β, IL-6, prostaglandin E2 (PGE2) and granulocyte-macrophage colony-stimulating factor (GM-CSF)." (PMID 31428574, 2019). "Our results indicate that coculture with primary NSCLC cells downregulates the production of IL-6, IL-12, and IL-23 by CD1c+ DCs compared with that of CD1c+ DCs that are not cocultured with primary tumor cells." (PMID 31921114, 2019). "In the tumor biopsies, the expression of these cytokines was notable at the level of the invasion front of the tumors for TGF- β and in the tumor (40% cases) and in the stromal areas (100% cases) of the invasive tissues for IL-6." (PMID 31885577, 2019). "Overexpression of the cancer progression-associated miR-146a in MSC after incubation with exosomes from the MM cell lines RPMI 8226, OPM-2, LP-1, and U266 induces secretion of IL-6, CXCL1, IP-10 (interferon gamma-induced protein 10), and CCL5 and enhances tumor cell survival and migration." (PMID 31281380, 2019). "Univariate analysis revealed that preoperative serum IL6 > 8.45 pg/ml, preoperative serum IL8 > 68 pg/ml, preoperative serum TNF − α > 14.9 pg/ml, MVI, and maximum tumor size > 5 cm were significantly correlated with RFS in HCC patients who accepted radical hepatectomy." (PMID 31781194, 2019). "The lack of efficacy of IL-6 pathway blockade in cancer is likely due to tumor cells plasticity, displaying different tumor clones in tumor samples in vivo." (PMID 32039001, 2019). "No 24-h differences among tumor treatments were observed for Il-6 in the hypothalamus or frontal cortex." (PMID 30679700, 2019). "The positive correlation between IL-6 and EMT in tumor microenvironment is reported." (PMID 31252615, 2019). "In fact, the entire process of IL-6 release from contracting skeletal muscles appeared to be unique as intravenous injections of IL-6 failed to reduce tumor growth." (PMID 31244666, 2019). "Finally, we found that administrating SFN inhibited the formation of THBE xenograft tumors in NOD/SCID mice and reduced the levels of IL-6, ΔNp63α, NICD, Hes1, and lung CSC markers in THBE xenograft tumor tissues." (PMID 31367260, 2019). "IL-6 expression was strongly and consistently enhanced in PDT-treated mice, although the role of IL-6 in PDT-induced inflammation may vary depending on the PS, protocol or type of tumor treated." (PMID 31861531, 2019). "Irradiation might induce interleukin-6 and lead to activation of JAK/STAT3 signaling in both tumor cells and tumor-infiltrating immune cells, which can promote tumor cell proliferation, survival, invasiveness, and metastasis." (PMID 31126307, 2019). "We performed an IHC investigation of the neoplastic lesions so as to see if the IL-6 mRNA and protein detected in the saliva of patients with OSCC might be produced by cells in the tumor tissue." (PMID 31766212, 2019). "Moreover, these therapies can trigger a cytokine storm in the tumor stroma, such as the release of IL-6 and TNF-α, as well as activate macrophages to generate pro-inflammatory mediators to stimulate tumor growth and contribute to recurrence." (PMID 30999932, 2019). "We observed a highly negative correlation between the tumor purity and IL6 mRNA (r = − 0.6274; ****P < 0.0001." (PMID 30744595, 2019). "Three fractions of RT also significantly increased the plasma concentrations of IL-6 and TNFα in the normal mice, but not in the tumor-bearing mice." (PMID 31752313, 2019). "Consistent with this scenario, it was reported that osteoblasts precursors secrete significant higher levels of IL-6, IL-10, BAFF, HGF, and VEGF, suggesting that suppression of osteoblast differentiation enhances tumor growth by creating a tumor permissive microenvironment." (PMID 30770859, 2019).
tumor (continued). "Accordingly, pharmacological blockade of C5aR1 in a syngeneic model of lung cancer impaired tumor growth, decreased the percentage of splenic MDSCs, and downregulated immunosuppression-related genes including ARG1, IL6, IL10, CTLA4, LAG3, and PDL1 within the tumor milieu." (PMID 31001273, 2019). "In addition, SOD2 mediated cell invasion induced by extracellular factors, such as IL-6 and SULF2, suggesting that SOD2 plays an essential role in cell invasion induced in response to tumor microenvironment changes." (PMID 30755594, 2019). "Furthermore, increased IL-6 stimulates the activation of JAK/STAT3 signaling, functioning as transcriptional activators of STAT3 mediated target genes, which results in tumor proliferation, and/or survival." (PMID 31817563, 2019). "The IL-6/STAT3 pathway facilitates the expansion of immunosuppressive cells or changes the balance of T cell subsets, such as T regulatory cells and MDSCs, which promote tumor growth." (PMID 31640814, 2019). "In addition, a decrease in oxygen availability causes an increase in the expression of the cytokines IL-1ẞ, IL-6 and TNF-α, which in turn promotes tumor progression by stimulating VEGF expression." (PMID 31568519, 2019). "Taken together, in this study, the acquisition of 5FU and Dox chemoresistance in DP-HCC1806:BMMSCs is likely due to a CAM-DR mechanism, in which CD9, IL6, and CCL5/CCR5 collectively mediate tumor-growth, adhesion and anti-apoptotic signals, via integrin-dependent mechanisms." (PMID 31191817, 2019). "In the mouse B16 tumor model, activated S1PR1 can accelerate tumor progression by activating STAT3 and upregulating IL-6, and this relationship between S1PR1 and STAT3 has been shown to contribute to chronic intestinal inflammation and colitis-associated colon cancer." (PMID 31807117, 2019). "And inhibitors of IL-6, IL-6R, GP130, JAK, and STAT3 may be targets for tumor therapy in the future." (PMID 31832112, 2019). "In addition, CAF can recruit regulatory DCs through IL-6-mediated STAT3 activation and educate them to obtain a tolerogenic phenotype and up-regulate Treg production by secreting TGF-β in the tumor microenvironment." (PMID 31464625, 2019). "Breast and gastric tumor-derived exosomes can induce a M1 pro-inflammatory response in macrophages through the activation of NFκB, which in turn stimulates production of inflammatory cytokines including GCSF, IL-6, IL-8, IL-1β, CCL2, and TNF-α." (PMID 31555295, 2019). "MDSCs can secrete IL-6 and TNF-α, which can promote tumor growth." (PMID 31832112, 2019). "In addition to an intrinsic cell-autonomous tumor-suppressive mechanisms, SASP components such as IL-6 and IL-8 have been shown to reinforce senescence in an autocrine manner." (PMID 31137607, 2019). "We used IL6-treated tumor cells as a positive control and also observed no supershift by anti-pSTAT3 antibody." (PMID 31228946, 2019). "Evidences at both transcriptional and translational levels as well as functional studies using established stable cells with FA2H modulation suggested the tumor suppressive roles of FA2H on cancer stemness and cell migration via inhibiting the STAT3/IL6 axis and NFkB mediated signaling." (PMID 31709178, 2019). "In addition, significant positive correlations were found between change in IL-6 concentration and EORT QLQ C30 pain (r=0.404; P=.01), with weight (r=0.301; P=.06) and with type of tumor removal surgery (r=0.311; P=.05)." (PMID 31414667, 2019). "Interleukin 6 has also been shown to play key functions in multidrug resistance via JAK, STAT3, PI3K/Akt, and Ras-MAPK signal pathways, tumor cell migration, invasion, and other pathways of carcinogenesis." (PMID 31572184, 2019). "Moreover, IL-6, phosphorylated STAT3 and STAT3 transcriptional activity were consistently upregulated in tumor-spheres from ESE3/EHF under-expressing tumor cells, in line with aberrant activation of IL-6/JAK/STAT3 pathway in prostate CSC." (PMID 31143708, 2019).
tumor (continued). "In addition to EGF, IL-6 is another oncogenic cytokine, and its activation can induce STAT3 and AKT signaling, resulting in tumor growth and invasion in numerous cancers, including cervical." (PMID 31235851, 2019). "Besides IFN-γ, we also examined many other immune cytokines involved in the anti-tumor response of CT26, such as IL-12, from Th1 cells; IL-6 from antigen-presenting cells; and TNF-α from macrophages." (PMID 31456687, 2019). "Based on the evidence that exogenous rAPE1 may trigger expression of both IL-6/8 cytokines, we may hypothesize that secreted APE1 may act as a paracrine molecule in regulating tumor microenvironment cell decision fates." (PMID 30719231, 2019). "Similarly, in tumor tissues of CMS-induced mice, the expression and phosphorylation of ABL1, p-NF-κB1, p-STAT3, IL-6, IL-1β, and COX2 significantly increased." (PMID 31396300, 2019). "TAMs produce growth and survival factors for tumor cells (e.g., EGF, fibroblast growth factor [FGF], IL-6, and IL-8) and angiogenic factors (EGF, FGF, vascular endothelial growth factor [VEGF], PDGF, TGF-β, and CXC chemokines) and suppress the T-cell dependent antitumor immunity." (PMID 31277406, 2019). "Recently a study has determined that tumor-derived exosomes (TEX)-activated dendritic cells (Ta-TEXs) are able to increase the production of inflammatory mediators of dendritic cells, which include IL-6 and prostaglandin E1 (PGE1)." (PMID 31555295, 2019). "Enhanced production of PGE2, IL-1β, IL-6, TGF-β as well as arginase, indoleamine 2,3-dioxygenase (IDO) and IL-10 from MDSCs implicitly mediate reciprocal differentiation of Th17 and Treg cells in a defined circumstance of tumor microenvironment." (PMID 31024835, 2019). "Furthermore, we investigated the contribution of IL-6, IL-8 and the JAK2/STAT3 signaling pathway to the pro-tumor effect of GC-MSC-primed macrophages." (PMID 31801938, 2019). "While tumor proliferation was reduced in xenografts, the invasive phenotype induced by CRYβB2 overexpression was not decreased when IL6 was inhibited in 3D cultures." (PMID 31511085, 2019). "Pulsing BMCs with DRibbles increased the in vitro production of pro-inflammatory cytokines IL-6, IL-1β, IL-12 and Type I IFNs and replacing DR-pulsed-BMCs with DRibbles also delayed tumor growth kinetics, albeit not as prominently." (PMID 31747946, 2019). "Among the tumor-derived soluble factors that contribute to immune cell suppression are vascular endothelial growth factor (VEGF), tumor necrosis factors (TNFs), TGF-β, IL-1, IL-6, IL-10, prostaglandin E2 (PGE2), Fas, and Fas-L." (PMID 31750245, 2019). "Il-6 levels did increase over time in some patients with lower baseline levels of IL-6 but these changes occurred gradually and similar to the observed gradual increase in VEGF or HGF levels likely reflecting corresponding increases in tumor burden/progression." (PMID 31426803, 2019). "However, it was found in another study that stimulation of the monocytic cell line THP1 with tumor-exosomes induced TNF-α, IL-1β, and IL-6 through TLR2 and TLR4 signaling." (PMID 29867942, 2018). "In addition, IDO1 plays a key role in promoting tumor neovascularization by modulating the expression of interferon-γ (IFN-γ) and interleukin-6 (IL-6)." (PMID 30068361, 2018). "IL-6, CRP, and MMP-9 serum levels showed very similar trends, increasing concomitantly and reaching the highest values in stage IV CRC, indicating they are involved in tumor promotion and proliferation." (PMID 30154846, 2018). "Interestingly, activated T cells can enhance HSC activation, resulting in IL-6, IL1-α, and TGFβ production, thus adding to the inflammatory milieu of cytokines promoting tumor growth." (PMID 30150983, 2018). "Inflammatory cell infiltration, including macrophages and neutrophils, was observed in tumor specimens compared to the non-cancer portion, and inflammatory cytokines such as IL-6 were upregulated." (PMID 30532127, 2018).
tumor (continued). "IL-6 mediates chemotaxis, which facilitates MSC attraction into the main tumor growth sites." (PMID 29615915, 2018). "IL-6 (Interleukin-6) and GP130 are part of the IL-6/JAK/STAT3 pathway that is involved in proliferation, survival, invasiveness and metastasis of tumor cells and in suppression of the anticancer immune response, and constitutes an attractive target for anti-cancer therapies." (PMID 30190791, 2018). "The immunohistochemical analysis of the tumor tissues also showed a negative correlation between IL-6 and TIMP3 expression." (PMID 29731768, 2018). "Because it has been reported that the tumour‐derived factors such as CCL2, SDF1, IL6, TNFα, VEGF, G‐CSF, TGFβ, and CXCL1 function in the pre‐metastatic phase, we applied those factors to HepELs in the tumour‐bearing mouse liver in vitro." (PMID 29930175, 2018). "Since IL-6 acts differently from TNF-α, and can be replaced by other cytokines, we think that TNF-α is the first endogenous instigator for the sequence of cytokine cascade from IL-1 to IL-6 and subsequently returns to TNF-α in tumor promotion." (PMID 30341686, 2018). "MLC obtained from tumor-bearing animals secreted large amount of IL-6 even in the absence of a challenge." (PMID 29721190, 2018). "Furthermore, IL-6 induces the production of vascular endothelial growth factor (VEGF), which promotes angiogenesis and neovascularization in the tumor microenvironment." (PMID 29772694, 2018). "Importantly, the GLPS and triterpene acid were demonstrated to promote the production of cytokines, such as IL-1β, IL-4, IL-6, IL-12, IL-17, RANTES, TNF-α and IFN-γ, and thus to exhibit immuno-modulation and anti-tumor activities." (PMID 30139984, 2018). "However, when the tumor cells were also stimulated with the type 1 cytokine IFNγ and TNFα an increased expression of CCL2, CCL5, CXCL9, CXCL10 and IL-6 was detected when compared to treatment with the control antibody." (PMID 30192802, 2018). "In contrast, the pro-inflammatory cytokines like interleukin-6 (IL-6), IL-1, and tumor necrosis factor alpha (TNF-α) secreted by tumor cells may inhibit TG synthesis." (PMID 30400953, 2018). "Tumour cells increase CRP expression by producing inflammatory proteins, including CRP or by enhancing the role of inflammatory cytokines such as IL-6 and IL-8, which could indirectly increase the CRP level." (PMID 29890986, 2018). "We concluded that IL-6-related tumor-derived soluble factors, but not IL-6 directly, affected the development of e-MDSCs." (PMID 30083161, 2018). "Above data suggested that tumor-derived IL-6 mainly affected the immune state in tumors, rather than the systematic environment." (PMID 30083161, 2018). "For example, IL-6 up-regulates Mcl-1 gene transcription through p38-MAPK and JAK-STAT pathways, inhibiting tumor necrosis factor-relatedapoptosis inducing ligand (TRAIL)-induced tumor cells apoptosis." (PMID 30216977, 2018). "Furthermore, ERβ regulates IL6 expression via MAPK/ERK and PI3K/AKT pathways when stimulated by E2 and promotes cell malignancy in vitro and induced tumor growth in vivo." (PMID 29970138, 2018). "Moreover, IL-6, together with TGF-β, affects the balance between Tregs and Th17 cells, reducing the tumor-suppressive Tregs and promoting the differentiation of pro-inflammatory, Th17 cells." (PMID 30154786, 2018). "Furthermore, tumor tissues co-injected with DCIS.com and preadipocytes displayed stronger IL-6 staining than those injected with DCIS.com alone." (PMID 30134951, 2018). "In addition, IL-6 can induce the expression of G3BP1, while G3BP1 depletion diminishes the IL-6-elicited STAT3 activation and leads to inhibition of tumor cell growth and invasion in RCC." (PMID 29717134, 2018). "NF-κB-dependent IL-6 production and the downstream STAT3 signaling have been demonstrated to promote neoplastic cell proliferation and survival, as well as induce chemoresistance of diverse tumor cell lines in vitro." (PMID 30042442, 2018).
tumor (continued). "TNFα released by tumor cells and cells of TME acts through its receptor TNFR1 and further reinforces TNFα expression and the inflammatory and immune-modulatory network including CXCL12, CCL2, IL-6, VEGF, and macrophage inhibitory factor." (PMID 30154786, 2018). "Conversely, in THP-1 cells, the decrease in TNF-α, IL-6 and IL-1β levels by WRE may prevent excessive activation of NF-κB, diminish cytokine induced tumour immunosuppressive activity and cancer progression." (PMID 29631586, 2018). "These stromal cells will secrete paracrine growth signals such as vascular endothelial growth factor (VEGF), insulin-like growth factor (IGF), interleukin-6 (IL-6), Wnt, Platelet-derived growth factor (PDGF), and Bone morphogenetic proteins (BMP) to induce the growth of the tumor." (PMID 30423843, 2018). "Importantly, IL-6 and CCL2 production in mouse and human tumor epithelial cells is elevated with reduced IGF-1R function." (PMID 30458886, 2018). "In order to evaluate whether the combined expression of RANTES and IL-6 is able to induce a more aggressive tumor phenotype, we analyzed the migratory and invasive ability of MCF-7RANTES+IL6 and MDA-MB-231RANTES+IL6 cell lines." (PMID 29707128, 2018). "As LA1 stimulated Let7a expression and inhibited Pdgfb and Il6 expression, these results suggested that LA1 might stimulate pro-inflammatory immune responses that could inhibit tumor growth in vivo." (PMID 30568188, 2018). "Looking over the results of transcriptome analysis we found that most of the tumor-promoting growth factors, such as epidermal growth factor (EGF), hepatocyte growth factor (HGF), nerve growth factor (NGF) or interleukin 6 (IL-6) were expressed at similar level in ASC.B6 and vASC." (PMID 30185144, 2018). "In addition, the ascites are rich in soluble agents that support tumor growth and tissue neovascularization, including angiogenin, VEGF, IL-6, CCL2/MCP-1, CXCL1/GRO-1, and CXCL8/IL-8." (PMID 28956065, 2018). "In both orthograft and NPS models, IL6‐neutralising therapies did not alter the tumour burden in mock‐treated animals, indicating the importance of IL6 in tumour survival in the context of ADT." (PMID 29540470, 2018). "A recent investigation demonstrated that hypoxia together with some chemoattractants such as IL-6 and MCP-1 could recruit MSCs to tumor lesions." (PMID 29386041, 2018). "Furthermore, the osteoclasts are stimulated by tumor induced osteolytic factors (RANKL expression, Parathyroid hormone-related protein, Interleukin-6, matrix metalloproteinases and cathepsins)." (PMID 30326868, 2018). "Pre-stimulation of hMEC-1 or hTERT-LEC with either IL-6 or IL-10 did not significantly alter tumour cell adhesion patterns when compared to unstimulated conditions." (PMID 29256156, 2018). "For example, non-tumor cell-derived TNF-α, IL-6, IL-8, and IL-1β stimulate tumor cell proliferation, invasion, and metastasis via paracrine signaling." (PMID 30038719, 2018). "Hoshida and colleagues showed that pro-inflammatory gene expression (TNFα, IL-6, and nuclear factor-κB) in the NTME, rather than the tumor itself, strongly associated with poor prognosis and high recurrence rate in patients undergoing hepatic resection." (PMID 30150983, 2018). "Likewise, we also showed that TNFα up-regulate genes CLDN-1, IL6, and NFκBIA, which have previously been reported to increase OSCC cell proliferation, supporting our increased tumor volume findings." (PMID 30018735, 2018). "IL-6 is increased in the serum of CRC patients and impacts tumor grade and survival rate." (PMID 30591653, 2018). "We tested the situation where tumors cells were not able to produce IL-6 and found the final tumor sizes to be approximately 45% smaller without direct IL-6 signaling." (PMID 29351275, 2018). "Additionally, tumor cells have been proposed as a potential trigger for CRP upregulation, as they secrete IL-6 and 8 to stimulate liver CRP production." (PMID 29619344, 2018).